PPARG (peroxisome proliferator activated receptor gamma)
Diseases named in the same sentence as PPARG in open-access papers (continued):
Sharing a sentence is not in itself a finding about the gene and the disease.
metabolic syndrome (continued). "Furthermore, PPARγ agonists improve insulin resistance and dyslipidemia, despite the increase in fat mass." (PMID 34211632, 2021). "Thus, reduced PPARγ activity in APL cells decreased leptin but increased resistin expression, causing lipid metabolism disorder in hepatocytes and subsequent dyslipidemia in mice." (PMID 32929351, 2020). "PPARγ are key nuclear receptors and therapeutic targets for the treatment of metabolic diseases through the regulation of insulin resistance, diabetes, and dyslipidemia." (PMID 31993046, 2019). "Moreover, it has been shown that rosiglitazone restores endothelial dysfunction in a rat model of metabolic syndrome, through PPARγ- and PPARδ-dependent phosphorylation of eNOS and AKT." (PMID 31993046, 2019). "Evidence also showed that rs3856806 in PPARγ had a close relationship with metabolic syndrome, subjects with TT genotype had higher BMI in males, and those with TT/TC genotypes had higher systolic blood pressure, HOMA-IR, and larger body fat percentage, which were all related to insulin sensitivity." (PMID 29849618, 2018). "Future investigation of PPARγ may help clarify the pathogenesis of metabolic syndromes in humans and provide new methods for the prevention or treatment of CGD." (PMID 30105244, 2018). "In addition to its effects on myocardial remodeling AT contributed to the dyslipidemia in db/db mice and increased PPARγ expression." (PMID 30071860, 2018). "Although many of the results from the current study are consistent with previous reports using various models of metabolic syndrome, this is one of the most comprehensive studies using a single model to characterize both the syndrome and its attenuation by a PPARγ agonist." (PMID 28101123, 2017). "The PPARG gene plays an important role in adipocytes differentiation, insulin sensitivity regulation, and its variation has been reported association with some CAD related risk factors, such as T2DM or metabolic syndrome (MS)." (PMID 28415751, 2017). "PPARγ is a ligand-activated transcription factor that may provide a promising therapeutic approach for metabolic syndrome." (PMID 27853282, 2016). "However, more systemically used epigenetic and transcriptomic analyses are necessary in the different PPARγ mouse mutants for elucidating PPARγ and its cistrome’s role in metabolic syndrome." (PMID 27483259, 2016). "Likewise, another study also found an upregulation of PPARγ in the liver of metabolic syndrome rats given genistein aglycone." (PMID 26246839, 2015). "The PPARγ agonist stabilized the altered hepatic circadian-clock and related gene expression, implying that the peripheral circadian-clock system, especially in the liver, is an attractive therapeutic candidate for treating the metabolic syndrome." (PMID 25799429, 2015). "In addition, we showed that SCFAs protect against the metabolic syndrome via a signaling cascade that involves PPARγ repression and AMPK activation." (PMID 26292284, 2015). "Therefore, our effort has been to investigate PPARG expression in different tissues and cells—affected in metabolic syndrome—and during hMSCs' adipocyte differentiation." (PMID 24790595, 2014). "Thus, a better understanding of PPARγ signaling is crucial to develop more effective and targeted therapeutic strategies to treat metabolic syndrome and its complications." (PMID 24790595, 2014). "Human genetics has provided evidence of a role of PPARγ in the metabolic syndrome." (PMID 23431284, 2013). "Although a variety of PPARγ agonists are available, novel pharmacological agents would be needed in the therapeutic armament giving the recent escalation of insulin resistant T2D, metabolic syndrome, and cardiometabolic complications." (PMID 20508722, 2010).
metabolic syndrome (continued). "The importance of PPARγ : RXR interaction is seen in Familial Partial Lipodystrophy, an autosomal dominant condition associated with metabolic syndrome, characterized by dyslipidemia, abnormal adipose tissue distribution, and a number of metabolic abnormalities." (PMID 20182546, 2010). "We conclude that the expression of PPARγ gene is regulated by DNA methylation of its promoter region and propose that reduced expression of PPARγ owing to DNA methylation in adipocytes of the VAT may contribute to the pathogenesis of metabolic syndrome." (PMID 19589179, 2009). "In this study, we investigated the contribution of epigenetic transcriptional regulatory mechanisms, such as DNA methylation, to the expression of the PPARγ gene, and further evaluated the contribution of such epigenetic regulatory mechanisms to the pathogenesis of metabolic syndrome." (PMID 19589179, 2009). "Telmisartan, an antihypertensive agent with evidence of partial peroxisome proliferator-activated receptor activity-gamma (PPARγ) activity, may improve insulin sensitivity and lipid profile in patients with metabolic syndrome." (PMID 15892894, 2005). "This study demonstrated that (a) PPARγ agonists improved insulin sensitivity and ameliorated dyslipidemia in HF fed rats and ZDF rats, which were correlated with serum adiponectin; (b) Serum adiponectin was positively correlated with adipose FABP3 mRNA in GI262570-treated rats." (PMID 15491498, 2004). "Hence, we suggest that two phytochemicals that may be used for PPARγ activation and may befurther modified and synthesized to develop potential drug candidates against metabolic syndrome and especially T2DM." (PMID 37901293, 2023). "The gene and protein expression of PPARγ related to lipid biosynthesis, the specific regulation of Stearoyl ethanolamide, Mesalamine, Lipoic acid, Picrotin, Citicoline, Norbuprenorphine, and Oxoamide make a big effort to alleviate dyslipidemia in HFD mice under the treatment of CO." (PMID 35745155, 2022). "Thus, PPARγ is a possible target molecule for anti-inflammatory as well as metabolic syndrome." (PMID 33919837, 2021). "However exposure to PPARγ agonists during development can increase the number of fat cells produced during development, leading to an obese phenotype and development of metabolic syndrome in adults, marked by hyperinsulinemia, long after exposure to the PPARγ agonist has ceased." (PMID 30728429, 2019). "This may be attributed to the previously reported ability of OA to suppress CCAAT/enhancer binding proteins-α (C/EBPα) and peroxisome proliferator activated receptor-γ (PPARγ) expression which are known to be pro-lipogenesis in animal models of metabolic syndrome." (PMID 30669379, 2019). "Moreover, biochanin A may improve lipid profile as a peroxisome proliferator-activated receptor gamma (PPARγ) agonist and provide beneficial effects on metabolic syndrome such as hyperglycaemia." (PMID 29217997, 2017). "FABP4 is a direct target gene of PPARγ, and has been shown to activate multiple metabolic and inflammatory signal pathways in both adipocytes and macrophages, thus plays a critical role in insulin resistance, type 2 diabetes, atherosclerosis and other metabolic syndromes." (PMID 27294862, 2016). "Moreover, there are some evidences that activation of PPARγ pathway through involvement on changes of adipokines could affect on metabolic profiles in animal model of metabolic syndrome studies." (PMID 24330836, 2013). "However, it is the first study revealing the different effects of PPARγ and RBP4 polymorphisms on the metabolic syndrome after multivariate analysis adjusting for anti-retroviral drug, diet and drinking in HIV-infected patients receiving anti-retroviral therapy." (PMID 23145084, 2012).
metabolic syndrome (continued). "Agonists of peroxisome proliferator-activated receptors (PPARα, PPARγ, PPARδ) regulate lipoprotein metabolism, fatty acid oxidation, glucose homeostasis and inflammation, and therefore are used as anti-diabetic drugs for treatment of dyslipidemia and insulin insistence." (PMID 19636418, 2009). "This dual involvement of CB2R and PPARγ in mediating BCP effects has also been reported in models of systemic inflammation and metabolic dysfunction, including colitis, dyslipidemia, and collagen-induced arthritis." (PMID 40649806, 2025). "For example, PPARα agonists (fibrates), PPARγ agonists (thiazolidinediones -TZDs) and combined PPARα/γ agonists (glitazars) are therapeutic agents for CVD prevention, T2DM and dyslipidemia." (PMID 39062500, 2024). "↓BW, energy intake, liver oxidative stress and inflammation, hepatocyte steatosis; ↑Insulin resistance, dyslipidemia, hepatorenal function; ↓PI3K-Akt–mTOR axis, SREBP-1c/PPARγ." (PMID 37396125, 2023). "These lead to changes in key metabolic pathways, including inhibition of lipoprotein lipase, peroxisome proliferator-activated receptor-gamma (PPARꝩ) and glucose transporter (GLUT4), resulting in dyslipidemia, weight changes and dysglycemia." (PMID 37507703, 2023). "Next, we evaluated the implication on SFRP5, WNT5A and PPARγ in SAT and VAT according to metabolic syndrome presence and their components (T2DM, dyslipidaemia and hypertension)." (PMID 36077270, 2022). "Baicalin, and Baicalein, have been found to be active against metabolic syndrome by activation and upregulation of AMPK and PPARγ." (PMID 36501129, 2022). "In addition, we have previously associated the C248T SNP with statistically significant higher blood levels of total cholesterol and LDL-C (unpublished data), suggesting that CD24 may also play a role in dyslipidemia, possibly through regulation of PPARγ expression." (PMID 33467499, 2021). "The TRIB3 expression that was increased by ATRA/As2O3 treatment further impeded PPARγ activity by forming the heterotrimer of TRIB3, PML-RARα and PPARγ, contributing to dyslipidemia in APL patients undergoing anti-APL therapy." (PMID 32929351, 2020). "trans-Vaccenic acid was shown to activate the transcriptional activity of PPARγ and/or PPARα in the JCR:LA-cp rat model of dyslipidemia and metabolic syndrome and in PBMCs." (PMID 31782488, 2020). "The elevated TRIB3 expression in response to arsenic/ATRA therapy suppressed PPARγ activity by disrupting the PPARγ/RXR dimer, which resulted in dyslipidemia in APL patients undergoing therapy." (PMID 32929351, 2020). "EWH upregulated the expression of anti-inflammatory molecules such as PPARγ and adiponectin, demonstrating the potential benefits of EWH on adipocyte function and metabolic syndrome." (PMID 28972997, 2017). "It has recently been reported that betahistine and OLZ co-treatment ameliorated OLZ-induced weight gain and dyslipidemia through the modulation of histaminergic, AMPKα–SREBP1, and PPARγ-dependent pathways." (PMID 27834848, 2016). "Here we describe a complete expression analysis of all annotated PPARG transcripts—PPARG1, PPARG2, PPARG3, and PPARG4—as well as its dominant negative isoform γORF4 in human tissues and cells affected in metabolic syndrome." (PMID 24790595, 2014). "Thus, defining PPARG activity in tissues and cells related to energy metabolism may provide useful insights to develop new and effective therapeutic strategies to treat the metabolic syndrome and its complications." (PMID 24790595, 2014). "PPARγ agonists regulate multiple processes, including Aβ homeostasis through the suppression of BACE1 expression, energy metabolism, insulin sensitivity, dyslipidemia, and microglial inflammatory responses." (PMID 25356910, 2014).
metabolic syndrome (continued). "The PPARs have already yielded viable targets for the treatment of T2DM and dyslipidemia; thiazolidinediones, PPARγ agonists, are currently used in the clinic for the treatment of T2DM; and fibrates, PPARα agonists, are routinely used to treat dyslipidemia." (PMID 21843327, 2011). "Therefore, all the described phytochemicals in this review, which act as PPARγ agonists, may be suitable for the treatment of metabolic syndrome together with other compounds that can suppress inflammatory responses in a PPARγ-independent manner, by directly inhibiting NF-κB or JNK signaling." (PMID 20508825, 2010). "On the other hand, daidzein, through its dual agonist activity on PPARα and PPARγ, could address T2DM-related dyslipidemia and vascular inflammation and mitigate glucose-induced damage in endothelial cells." (PMID 39768147, 2024). "The activation of PPARγ is a key mechanism for ameliorating hyperglycemia, and IR and PPARγ agonists, such as PIO, increase insulin sensitivity and ameliorate hyperglycemia, dyslipidemia, OS, and inflammation." (PMID 37397470, 2023). "Moreover, apigenin can also downregulate PPARγ and CEBP-α in the early phase of adipogenesis in 3T3-L1 adipocytes and protect against high-fat diet- (HFD-) induced metabolic syndrome in rats." (PMID 36092543, 2022). "ZNF384 is the potential transcription factor that may modulate STFs PPARG, ZNF415, HLX, and ANHX, thus subsequently triggering hyperinflammatory states and metabolic syndromes." (PMID 35669784, 2022). "One possibility is that Sparcl1 might regulate the PPARγ signal pathway and LPL expression, thereby regulating lipid metabolism and the development of dyslipidemia." (PMID 36387870, 2022). "The anti-dyslipidemia effects may be involved in the downregulation of adipogenic and lipogenic genes (C/EBP-α/-β, SREBP1, PPARγ, and FAS) and the upregulation of genes exerting transcriptional roles in lipolysis and β-oxidation (PPARα and UCP2)." (PMID 35326230, 2022). "Given that PML-RARα inhibited PPARγ activity in APL cells, we next examined whether ATRA/As2O3 rescued PPARγ activity and improved dyslipidemia in APL patients by decreasing PML-RARα expression." (PMID 32929351, 2020). "Conversely, activation of PPARγ with RGZ resulted in significant attenuation of nearly every measured parameter of the AROS axis, as well as attenuation of the defining parameters of the metabolic syndrome itself (downward green arrows)." (PMID 28101123, 2017). "PPARγ activation is known to modulate metabolic syndrome; however a systems-level investigation looking at the protective effects of PPARγ activation as related to the AROS axis has not been performed." (PMID 28101123, 2017). "However, although ATRA/arsenic treatment degraded PML-RARα and restored PPARγ expression, it did not improve but rather exacerbated dyslipidemia in these APL patients." (PMID 32929351, 2020). "The PPARG gene, located at 3p25-24, and plays a non-ignorable role in adipocytes differentiation, insulin sensitivity regulation, and its variation has been reported association with some CAD related risk factors, such as T2DM or metabolic syndrome (MS)." (PMID 28415751, 2017). "The aim of this work is to simultaneously characterize multiple molecular parameters within the AROS axis, using samples taken from different body fluids and tissues of a rat model of HFD-induced metabolic syndrome, in the presence or absence of a PPARγ agonist, Rosiglitazone (RGZ)." (PMID 28101123, 2017). "Because activation of FXR is a defined target in treating metabolic syndrome and specific ligands for this receptor are tested in NASH patients our data suggest, that similarly to PPARγ, activation of FXR might contribute to the beneficial effects observed under VSL#3 intervention." (PMID 23029000, 2012).
metabolic syndrome (continued). "In addition, the expression of PPARγ genes that correlated with the BCAA and serum lipid biomarkers were compared, and significant inhibition was noticed, which might lead to the potential exposure of the anti-dyslipidemia mechanism of CO in HFD-fed mice." (PMID 35745155, 2022). "Thus, whether Rg3 have effects on regulating PPARγ in dyslipidemia induced AS which interfere FAK-related pathways or not have yet to be explored." (PMID 32390845, 2020). "The observation that anti-APL therapy reduced PML-RARα and enhanced PPARγ but could not normalize dyslipidemia in APL patients indicates that other important regulator(s) may participate in the regulation of lipid metabolism disorder in APL patients during induction therapy." (PMID 32929351, 2020). "Since TTA might be used in the treatment of metabolic syndrome, it is of importance to show that TTA has no harmful effects on bone like PPARγ agonists as glitazones." (PMID 22190907, 2011). "Although the protein expression of PPARγ decreased in HFD mice, IRW treatment did not exhibit any effect on PPARγ protein abundance, suggesting that IRW might only be able to regulate PPARγ in the skeletal muscle of the mice with HFD-induced metabolic syndrome." (PMID 37106756, 2023).